STAT3 (signal transducer and activator of transcription 3)
Diseases named in the same sentence as STAT3 in open-access papers (continued):
Sharing a sentence is not in itself a finding about the gene and the disease.
cutaneous T-cell lymphoma (15 papers, 2015 to 2026). "The PLCG1/PKCθ axis accelerated STAT3 activation and promoted the proliferation and survival of cutaneous T-cell lymphoma cells." (PMID 36920176, 2023). "The mutation and loss of DDX3X in cell lines originated from DLBCL, cutaneous T-cell lymphoma (CTCL), and NK-cell/T-cell lymphoma (NKTCL) enhanced proliferation and STAT3/p42/p44 phosphorylation." (PMID 35874614, 2022). "In another study, STAT3 was shown to inhibit miR-22 expression in patients with cutaneous T-cell lymphoma." (PMID 32811699, 2020). "Acquired mutations were recently described in cutaneous T-cell lymphomas for the JAK1, JAK3, STAT3, and STAT5B genes of the JAK-STAT pathway." (PMID 29262599, 2017). "Increasing evidence supports a potential role for STAT3 as a tumor driver in cutaneous T-cell lymphomas (CTCL)." (PMID 33333886, 2020). "Also, recent study suggests an IL-22/STAT3/CCL20 signal cascade in cutaneous T-cell lymphoma." (PMID 26901187, 2016). "Skin colonization by this bacterium could be involved in the hyperactivation of the STAT3 inflammatory pathway and in the overproduction of IL-17, both of which are widely related to the development of more aggressive and advanced forms of cutaneous T-cell lymphoma." (PMID 38435536, 2024). "Inhibition of Jak3, STAT3 and STAT5 triggered overexpression of miR-22 and suppressed cancer proliferation in cutaneous T-Cell lymphoma." (PMID 28548950, 2017). "Aberrant activation of Janus kinase-3 (Jak3) and its key down-stream effectors, Signal Transducer and Activator of Transcription-3 (STAT3) and STAT5, is a key feature of malignant transformation in cutaneous T-cell lymphoma (CTCL)." (PMID 26244872, 2015).
hyperuricemia (15 papers, 2021 to 2025). An abnormally high level of uric acid. "Therefore, we introduced sIL-6R to demonstrate that hyperuricemia-induced STAT3 activation is associated with IL-6." (PMID 40361044, 2025). "This study aimed primarily to elucidate the role of HMGCS2 and the JAK2/STAT3 signaling pathway in hyperuricemia-induced mitochondrial dysfunction." (PMID 40361044, 2025). "In conclusion, these findings demonstrate that inhibiting the JAK2/STAT3/HMGCS2 signaling pathway with ruxolitinib and S3I-201 alleviates mitochondrial dysfunction, oxidative stress, and cardiac dysfunction caused by hyperuricemia." (PMID 40361044, 2025). "On the other hand, the Janus kinase 2/signal transducer and activator of transcription 3 (JAK2/STAT3) signaling pathway was inhibited in the liver of the mouse model with hyperuricemia." (PMID 38042879, 2023). "STAT3 activation induced by hyperuricemia in tubular and interstitial cells was accompanied by kidney fibrosis and dysfunction, and the STAT3 inhibitor S3I-201 was confirmed to suppress the JAK-STAT pathway to achieve anti-fibrotic effects." (PMID 37208335, 2023). "And another recent document illustrated that the phosphorylation levels of JAK2 and STAT3 were upregulated in the kidney of hyperuricemia mice." (PMID 36248423, 2022). "Similarly, treatment with the JAK inhibitor ruxolitinib also significantly lowered the phosphorylation levels of JAK2 and STAT3 induced by hyperuricemia, achieving effects comparable to those of STAT3 knockout." (PMID 40361044, 2025). "Berberrubine has also been shown to reduce hepatic XOD activity, downregulate the expression of Glut9 and Urat1 and upregulate the expression of Oat1/3 and Abcg2 at both the protein and mRNA levels in mice with hyperuricemia as well as to suppress activation of the JAK/STAT3 signaling pathway." (PMID 36483739, 2022). "However, whether hyperuricemia activates the JAK2/STAT3 signaling pathway in cardiomyocytes remains to be further investigated." (PMID 40361044, 2025). "Model of hyperuricemia-induced mitochondrial dysfunction and oxidative stress in cardiomyocytes involving JAK2/STAT3/HMGCS2 signaling." (PMID 40361044, 2025). "PP1 treatment also inhibited hyperuricemia-induced activation of the TGF-β1/Smad3, STAT3, ERK1/2, and NF-κB signaling pathways and expression of multiple profibrogenic cytokines/chemokines in the kidney." (PMID 38576481, 2024). "Pharmacological inhibition of the activation of the JAK/STAT3 pathway has been shown to reduce serum urate levels and delay the progression of kidney fibrosis and CKD in adenine- and PO-induced hyperuricemia mouse models." (PMID 36483739, 2022). "In addition, in vitro, the JAK inhibitor ruxolitinib can alleviate hyperuricemia-induced mitochondrial dysfunction and oxidative stress by affecting the JAK2/STAT3/HMGCS2 signaling pathway." (PMID 40361044, 2025). "Our study revealed that hyperuricemia significantly increased the phosphorylation levels of JAK2 and STAT3 in AC16 cardiomyocytes and myocardial tissue from hyperuricemic mice, whereas the total protein levels of JAK2 and STAT3 remained unchanged." (PMID 40361044, 2025). "Fisetin (3,3′,4′,7-tetrahydroxyflavone), a naturally occurring flavonol, reduces serum urate by modulating the expression of kidney urate transporters, including Urat1, Oat1/3, and Abcg2, via the STAT3 and TGF-β signaling pathways in mice with PO- and adenine-induced hyperuricemia." (PMID 36483739, 2022). "Intervention targeting the phosphorylation of JAK2 and STAT3 may inhibit the JAK2/STAT3/HMGCS2 signaling pathway, thereby alleviating hyperuricemia-induced mitochondrial dysfunction, oxidative stress, and energy metabolism disorders, and potentially improving heart dysfunction." (PMID 40361044, 2025). "Western blot analysis showed that hyperuricemia significantly increased JAK2 and STAT3 phosphorylation in cardiac tissue without altering total protein levels." (PMID 40361044, 2025).
infarction (15 papers, 2008 to 2025). A localised pathological necrosis of tissue resulting from obstruction of the blood supply usually by a thrombus, an embolus, or vascular torsion. "Dapagliflozin can mediate M2 polarization via the STAT3 pathway, thereby reducing myofibroblast infiltration during post-infarction remodeling." (PMID 39539627, 2024). "We found that n‐butylidenephthalide administration even after infarction is sufficient to rejuvenate the age‐associated impairment in macrophage polarization, mainly through activation of the PI3K/STAT3 axis." (PMID 31313516, 2019). "Pharmacological inhibition of Stat3 reversed protective effects of decreased infarction volumes and short-term behavior after HIE when applied in combination with intranasal IFNβ treatment." (PMID 27683877, 2016). "Moreover, inhibition of the JAK/STAT pathway by AG490 significantly inhibited STAT3 phosphorylation in rat hearts and increased caspase-3 activity and Bax expression in viable myocardium following infarction." (PMID 31709266, 2019). "In conclusion, treatment with G-CSF at a small dose but for a long duration beneficially affects the post-infarction process possibly through STAT3-mediated anti-cardiomyocyte degeneration and anti-fibrosis, but not through anti-cardiomyocyte apoptosis or Akt-mediated angio-genesis." (PMID 18298650, 2008). "In an infarction model in non-diabetic rats, dapagliflozin increased signal transducer and activator of transcription 3 (STAT3) activity, STAT3 nuclear translocation, and M2 macrophage infiltration." (PMID 33754074, 2021).
lung diseases (15 papers, 2013 to 2025). "Intracellular signaling mediated by STAT3 has been implicated in lung inflammation and in the pathogenesis of various lung diseases." (PMID 33260937, 2020). "The activation of the STAT3 pathway and, consequently, the induction of NF- κB transcription factor regulate the expression of genes associated with inflammation in lung diseases and are correlated with disease severity." (PMID 32330145, 2020). "Intracellular signaling mediated by STAT3 has been implicated in lung inflammation and in the pathogenesis of various lung diseases that affect men and women differentially." (PMID 26949510, 2016). "Currently, direct STAT3 targeting primarily focuses on inhibiting functional dimerization by blocking its SH2 domain—the pivotal mediator of STAT3 dimerization and one of the most rapidly advancing therapeutic targets in pulmonary diseases." (PMID 40969747, 2025). "The molecular cascades of PTPN6/STAT3/PDCD4 play a vital role in Al2O3 NPs-involved pulmonary disorders." (PMID 29233151, 2017). "Activation of STAT3 can influence the expression of multiple genes involved in inflammatory responses, cell proliferation, and survival—critical processes for the pathogenesis of lung diseases." (PMID 40129771, 2025). "Even so, several STAT3-targeting inhibitors are under clinical evaluation for pulmonary diseases." (PMID 40969747, 2025). "The quality of life in patients with STAT3-HIES is determined by not only the progressive, life-limiting pulmonary disease, but also significant skin disease including recurrent infections and abscesses requiring surgery." (PMID 33523338, 2021). "So far, as already cited above, STAT3, controlled by the EGFR/ADAM17 axis, is a modifier of CF lung disease." (PMID 29540993, 2018).
lupus nephritis (15 papers, 2015 to 2025). Glomerulonephritis in the context of systemic lupus erythematosus. "Besides, previous studies have indicated that loss of STAT3 in T cells abrogated lupus nephritis (LN) and STAT3 pathway was involved in DN T cell proliferation." (PMID 34552214, 2022). "For example, IL-22 in renal epithelial cells of MRL/lpr mice has been found to bind to IL-22R to activate the STAT3 signaling pathway, enhance chemokine secretion, and promote macrophage infiltration into the kidney, exacerbating lupus nephritis." (PMID 35197962, 2021). "Indeed, administration of a STAT3 inhibitor to MRL/lpr mice delays the onset of lupus nephritis in Ref." (PMID 29868033, 2018). "Hence, HDW might ameliorate lupus nephritis by inhibiting IL-6 secretion and STAT3-induced IL-17 expression." (PMID 35958622, 2022). "STAT3/IL-17 may be a potential pathway target of Hedyotis diffusa Willd to treat lupus nephritis." (PMID 35958622, 2022). "Through this study, we concluded that OSM is associated with TIL in lupus nephritis, which may be connected with the activation of STAT3 rather than that of STAT1." (PMID 28626343, 2017). "Artesunate reportedly attenuated STAT1 phosphorylation in cultured HUVECs stimulated with IFNα and suppressed phosphorylation of JAK2 and STAT3 in the kidney of MRL/lpr mice, resulting in an amelioration of the symptoms of lupus nephritis." (PMID 34567013, 2021). "Rapamycin reduces both the activation of STAT3 and the number of IL-17 producing cells in patients with SLE, and decreases the severity of lupus nephritis and prolongs survival in MRL/lpr mice." (PMID 29868033, 2018). "Thus, we concluded that OSM is associated with TIL in lupus nephritis, which may be connected with the activation of STAT3 rather than that of STAT1." (PMID 28626343, 2017).
Peritoneal Fibrosis (15 papers, 2017 to 2024). Disorder characterized by a wide range of structural changes in PERITONEUM, resulting from fibrogenic or inflammatory processes. "Furthermore, the expression of STAT3/HIF-1α signaling might underlay the EMT process of mesothelial cells so as to cause peritoneal fibrosis, while STAT3 blockade might be an effective therapy for PF in long-term PD patients." (PMID 34193173, 2021). "Additionally, suramin treatment may also affect Smad-independent mechanisms associated with peritoneal fibrosis such as inhibition of Stat3 and ERK1/2 phosphorylation." (PMID 31727005, 2019). "IL-6 is also considered an important cytokine in peritoneal fibrosis, leading to peritonitis and fibrosis development through the STAT3-dependent pathway." (PMID 38483736, 2024). "Given the co‐localization among α‐SMA and P‐STAT3 and decrease in fibrosis with inhibition of STAT3 in the mouse peritoneal fibrosis model, our findings suggest that STAT3 play a vital role in fibroblasts activation during peritoneal fibrosis." (PMID 38780509, 2024). "Our results suggested that STAT3 signalling played an important role in myofibroblast differentiation of peritoneal fibrosis." (PMID 38780509, 2024). "Recent studies have found that gefitinib, an inhibitor of EGF receptor (EGFR), can significantly improve peritoneal fibrosis in experimental mouse models by inhibiting STAT3 phosphorylation." (PMID 38780509, 2024). "The major finding of this study was that effect of STAT3 in fibroblast and inhibition of STAT3 exerted protective functions against the peritoneal fibrosis." (PMID 38780509, 2024). "In mouse models, intraperitoneal injection of high-glucose dialysate triggers phosphorylated activation of STAT3, resulting in macrophage infiltration, peritoneal fibrosis, and angiogenesis." (PMID 39749340, 2024). "Pharmacological inhibition of STAT3 markedly attenuate peritoneal fibrosis and STAT3 can be a potentially effective antifibrotic molecular‐target." (PMID 38780509, 2024). "In this study, we investigated the role of STAT3 in fibroblasts phenotype conversion and the effect of pharmacological blockade of STAT3 in the development of peritoneal fibrosis." (PMID 38780509, 2024). "Taken together, these findings suggested that STAT3 contributed to TGFβ‐induced and IL‐6/S‐induced activation of fibroblasts and was involved in progressive peritoneal fibrosis." (PMID 38780509, 2024). "The inhibitor sgi-201 targeting STAT3 effectively suppresses hyperglycemia-induced peritoneal fibrosis by inhibiting angiogenesis, macrophage infiltration, and HIF-1α expression." (PMID 39749340, 2024). "In conclusion, our findings suggested STAT3 signalling played an important role in peritoneal fibrosis." (PMID 38780509, 2024). "Studies from our group have demonstrated that the activation of EGFR/ERK/1/2/STAT3 signaling pathway is related to the progression of peritoneal fibrosis." (PMID 36911746, 2023). "A high level of phosphorylated STAT3 was found in fibrotic peritoneal fibrosis from patients with long-term peritoneal dialysis (PD)." (PMID 35585990, 2022). "Taken together, these findings identified a novel mechanism linking STAT3/HIF-1α signaling to peritoneal fibrosis during long-term PD treatment." (PMID 34193173, 2021). "A recent report showed that STAT3/HIF-1α signaling participates in peritoneal fibrosis during long-term peritoneal dialysis (PD) treatment." (PMID 34944635, 2021). "In our study, macrophages accumulated in the sub-mesothelial zone after injury, and blockage of STAT3 inhibited infiltration of macrophages together with attenuation of peritoneal fibrosis in mice." (PMID 34193173, 2021). "Daily intraperitoneal injection of high-glucose based dialysis fluid (HG-PDF) induced peritoneal fibrosis in the mice, accompanied by the phosphorylation of STAT3." (PMID 34193173, 2021).
Peritoneal Fibrosis (continued). "In recent years, we have reported that interleukin-6 (IL-6) drives a STAT3-dependent pathway that leads to structural and functional alterations of peritoneal membrane in a mouse peritoneal fibrosis model." (PMID 34193173, 2021). "We further examined the effect of STAT3 inhibitor S3I-201 on peritoneal fibrosis induced by HG-PDF in mice." (PMID 34193173, 2021). "It provided the first evidence that pharmacological inhibition of STAT3 signaling attenuated high glucose-mediated mesothelial cells EMT as well as peritoneal fibrosis." (PMID 34193173, 2021). "Studies from our group and others have demonstrated that activation of the EGFR/STAT3 pathway is involved in the progression of peritoneal fibrosis." (PMID 29179471, 2017). "NF-κB and STAT3 are two important transcriptional factors that are activated and involved in the process of peritoneal fibrosis." (PMID 29179471, 2017). "For example, IL-6 has been reported to shift the tissue repair to a chronic inflammatory state by signal transducer and activator of transcription 3(STAT3) signaling pathway in peritoneal fibrosis." (PMID 29218009, 2017). "Moreover, STAT3 plays an important role in the peritoneal fibrosis in an animal model of peritoneal fibrosis developed in mice." (PMID 38780509, 2024). "We used S3I‐201 to investigate whether inactivation of STAT3 played an anti‐fibrotic role in mouse peritoneal fibrosis model." (PMID 38780509, 2024). "Furthermore, STAT3 induced by IL‐6 trans‐signalling pathway mediate the fibroblasts of the peritoneal stroma contributed to peritoneal fibrosis." (PMID 38780509, 2024). "The phosphorylation of EGFR subsequently leads to the activation of several intracellular signaling pathways, including extracellular signal-regulated kinases 1/2 (ERK 1/2) and signal transducer and activator of transcription 3 (STAT3) during peritoneal fibrosis." (PMID 36911746, 2023). "In vivo effect of STAT3 inhibitor S3I-201 on the development of peritoneal fibrosis." (PMID 34193173, 2021). "Finally, peritoneal fibrosis was induced by daily intraperitoneal injection with peritoneal dialysis fluid (PDF) so as to explore the role of pharmacological blockade of STAT3 in this process." (PMID 34193173, 2021). "We have certified that the HG/STAT3/HIF-1α signaling pathway might play an important role in the pathogenesis of peritoneal fibrosis induced by high-glucose based dialysis fluid." (PMID 34193173, 2021). "To determine whether Src-mediated peritoneal fibrosis is related to these two signaling pathways, we also examined the effect of Src inhibition on the phosphorylation and expression of STAT3 and Akt." (PMID 29137389, 2017). "Similarly, in the present study, we found that pharmacological inactivation of STAT3 in cultured RPFs prevents TGF‐β‐induced myofibroblast differentiation and significantly decreases the TGF‐β‐stimulated collagen release, suggesting the important role for STAT3 in driving peritoneal fibrosis." (PMID 38780509, 2024). "However, current studies on the role of STAT3 during fibroblasts in peritoneal fibrosis remains unclear." (PMID 38780509, 2024). "Therefore, blockade of STAT3 signalling might be a potential treatment strategy in peritoneal fibrosis." (PMID 38780509, 2024). "The mechanism may be that inhibition of core fucosylation of the EGF receptor inactivates the EGF signaling pathway by suppressing the phosphorylation of STAT3 and NF-κB in the peritoneal membrane of rats with peritoneal fibrosis, although further investigation is required." (PMID 33993842, 2021). "We previously reported that IL‐6 trans‐signalling activates signal transducer and activator of transcription 3 (STAT3) in human peritoneal mesothelial cells (HPMCs) and participate in the MMT process to promote peritoneal fibrosis." (PMID 38780509, 2024). "Therefore, blocking STAT3 might become a potential treatment strategy in peritoneal fibrosis." (PMID 38780509, 2024).